BRS3 (bombesin receptor subtype 3)
Description:
Role in sperm cell division, maturation, or function. This receptor mediates its action by association with G proteins that activate a phosphatidylinositol-calcium second messenger system.
Synonyms: BB3; BB3R; BBR3
Tractability: Small molecule: a structure with a bound ligand is known; a high-quality ligand is known; it belongs to a druggable protein family. Antibody: UniProt places it where antibodies can reach, with medium confidence; UniProt predicts a signal peptide or a membrane-spanning region; its Gene Ontology location is reachable by antibodies, with medium confidence. PROTAC: a small molecule that binds it is known.
Target class: GRP-related receptor; Short peptide receptor (family A GPCR); Membrane receptor; Family A G protein-coupled receptor; Peptide receptor (family A GPCR)
Chemical probes: AK120413 (high quality), CHEMBL1672352
Gene: Protein-coding gene on chromosome X (136,487,947 to 136,493,780, forward strand). Ensembl gene ENSG00000102239.
Subcellular location: Cell membrane
Pathways (Reactome):
Signal Transduction: G alpha (q) signalling events; Peptide ligand-binding receptors
Gene Ontology:
Molecular function: bombesin receptor activity; neuropeptide receptor activity; G protein-coupled peptide receptor activity; G protein-coupled receptor activity
Biological process: adult feeding behavior; G protein-coupled receptor signaling pathway; glucose metabolic process; regulation of blood pressure; bombesin receptor signaling pathway; neuropeptide signaling pathway
Cellular component: membrane; plasma membrane
Homologues: Orthologues: chimpanzee BRS3 (99% identical), macaque BRS3 (97% identical), rabbit BRS3 (91% identical), dog BRS3 (89% identical), pig BRS3 (87% identical), guinea pig BRS3 (86% identical), mouse Brs3 (85% identical), rat Brs3 (82% identical), tropical clawed frog brs3 (62% identical), Drosophila melanogaster CCHa1-R (33% identical), Drosophila melanogaster CCHa2-R (32% identical). Paralogues in human: GRPR (49% identical), NMBR (45% identical), EDNRB (27% identical), EDNRA (24% identical), GPR37 (22% identical), NTSR1 (20% identical), NMUR2 (20% identical), NMUR1 (20% identical), TRHR (20% identical), GHSR (19% identical), NTSR2 (19% identical), GPR37L1 (18% identical), and 3 more.
Diseases named in the same sentence as BRS3 in open-access papers:
BRS3 is named in the same sentence as 20 diseases in open-access papers, as found by Europe PMC text mining. Sharing a sentence is not in itself a finding about the gene and the disease. The quoted sentences say what the papers report.
Obesity (16 papers, 2010 to 2025). Accumulation of substantial excess body fat. "Both Cre recombinase insertions reduced Brs3 mRNA levels and BRS3 function, causing obesity phenotypes of different severity." (PMID 34326065, 2021). "Brs3-deficient mice develop obesity in association with a reduced metabolic rate and elevated feeding activity." (PMID 26020940, 2015). "Of note, in BRS-3 knockout (KO) mice, this receptor has been implicated in insulin release, as well as in the development of metabolic defects and obesity." (PMID 25653074, 2015). "One is the gene encoding CCDC80/URB/SSG1/DRO1, which was identified as an upregulated transcript in the adipose tissue of bombesin receptor subtype-3 (BRS-3)-deficient mice displaying mild late-onset obesity and sensitizes cells to anoikis and apoptosis." (PMID 20175888, 2010). "Notably, activation of PB-projecting PVH neurons expressing bombesin-like receptor 3 (Brs3) reduces food intake and silencing them causes obesity." (PMID 41282229, 2025). "Consequently, BRS3 gene inactivation in mice causes obesity, whereas synthetic agonists produce weight loss." (PMID 30840614, 2019). "Nevertheless, the precise neural pathway underlying the BRS‐3 agonist‐mediated anti‐obesity effect remains unclear." (PMID 29568682, 2018). "The anti‐obesity effect of the BRS‐3 agonist was still reportedly observed in Npy−/−, Mc4r−/−, Cb1r−/−, and Lepr−/− mice." (PMID 29568682, 2018). "The data suggest that the anti-obesity pharmacologic actions of BRS-3 agonists occur via agonism of receptors on glutamatergic neurons." (PMID 29107299, 2017). "Brs3 null mice have reduced resting metabolic rate and body temperature, increased food intake, and obesity." (PMID 29107299, 2017). "For example, Brs3 null (Brs3-/y) mice have a reduced fasting metabolic rate, resting heart rate, and body temperature, and increased food intake and obesity." (PMID 26562312, 2015). "BRS-3 is primarily expressed in the hypothalamus and plays a role in the onset of diabetes and obesity." (PMID 23293632, 2012). "However, BRS-3 has been identified as an important regulator of satiety, metabolic rate and obesity in the brain, glucose uptake in muscles, insulin secretion in β-cells, and glucose uptake and lipogenesis in adipose tissue." (PMID 35347148, 2022). "Single doses of a BRS3 agonist increased blood pressure in humans, likely via increased sympathetic tone, reducing interest in central agonism as a human therapeutic for obesity and stimulating interest in studying BRS3 agonists that do not enter the brain." (PMID 34326065, 2021). "Mice with knocked BRS-3 showed metabolic defects and developed obesity so ligands of mammalian BRS-3 might be an inhibitor of food intake." (PMID 34681728, 2021). "SCN may be involved in the BRS‐3 agonist‐mediated anti‐obesity effect via circadian rhythm regulation." (PMID 29568682, 2018). "As it is clear that BRS‐3 agonist finally exerts anti‐obesity effects, this NPY increase might be a compensatory reaction." (PMID 29568682, 2018). "However, our results strongly indicate that BRS-3 agonists achieve anti-obesity efficacy via activating glutamatergic neurons, likely chiefly in the brain." (PMID 29107299, 2017). "Since hyper-insulinemia is generally observed in genetically obese mice, the elevation of insulin is most likely the consequence of the obesity rather than the loss of Brs3 function." (PMID 26020940, 2015). "In muscle biopsies from patients with T2D (daily treatment with insulin prior to surgery), the decrease in the mRNA expression level of BRS-3 compared to the levels of the normal subjects was similar to the decrease detected in the muscle tissue sections from patients with obesity." (PMID 25653074, 2015). "Thus, the anti‐obesity effect of BRS‐3 agonist was considered to be mediated via the MCH pathway." (PMID 29568682, 2018).
Obesity (continued). "Similarly, Brs3, bombesin-like receptor 3, at 57 Mb on chromosome X, is a possible candidate for our proximal X obesity QTL since mice with mutations at this locus exhibit obesity, an impaired glucose metabolism, and a reduced metabolic rate." (PMID 24918027, 2014). "Thus, LPB and MHb could be involved in the anti‐obesity effect of the BRS‐3 agonist." (PMID 29568682, 2018). "Moreover, human skeletal muscle expresses functional BRS-3, and lower than normal BRS-3 mRNA/protein levels have been detected in patients with obesity and type 2 diabetes (OB/T2D)." (PMID 25653074, 2015). "The analysis of BRS-3 expression in the skeletal muscle of these patients revealed a marked decrease in the expression of BRS-3 at the mRNA (23.6±1.3-fold downregulation, p<0.0001) and protein level (49±7% decrease, p<0.05) compared to the normal patients (no obesity and diabetes)." (PMID 25653074, 2015). "Mice lacking functional BRS-3 develop metabolic defects and obesity." (PMID 23293632, 2012). "However, the expression level of BRS-3 in patients with OB/T2D reported in this study was much lower than that previously observed in patients affected by either T2D or obesity, thus suggesting a potential synergy in the negative impact of these 2 conditions on BRS-3 gene expression." (PMID 25653074, 2015).
lung carcinoma (3 papers, 2017 to 2024). "In the present study, small molecules were synthesized and their ability to antagonize BB1R, BB2R, and BRS-3 in lung cancer cells evaluated." (PMID 28785244, 2017). "Similar results were obtained for the bombesin receptor subtype-3 (BRS-3), a GPCR highly expressed in various tumors, such as breast cancer, lung cancer, and prostate cancer." (PMID 39698539, 2024). "The ability of BA1 to elevate cytosolic Ca2+ in human lung cancer cells transfected with BB1R, BB2R, and BRS-3 was antagonized by AM-37 and ST-36." (PMID 28785244, 2017). "For BRS-3, however, the novel BRS-3 antagonist ML-18, had anti proliferative effects in lung cancer." (PMID 29262666, 2017). "Because many lung cancer cells have BB1R, BB2R, and/or BRS-3 there is a need to develop antagonists that block all three receptors of the BB family." (PMID 28785244, 2017).
prostate carcinoma (3 papers, 2012 to 2024). A carcinoma that arises from epithelial cells of the prostate gland. "However, BBS acts on two other receptors, neuromedin B receptor (NMB-R) and BBS receptor subtype 3 (BRS-3), shown to be expressed in 14% and 9% of prostate carcinomas respectively." (PMID 22715899, 2012).
melanoma (2 papers, 2018 to 2025). A malignant, usually aggressive tumor composed of atypical, neoplastic melanocytes. "We recently found that BRS-3 was endogenously expressed in B16 cells, the murine melanoma cell line, and generated BRS-3 knockout B16 cells (B16-KO) using CRISPR-Cas9 techniques." (PMID 40141387, 2025).
neuroendocrine tumor (2 papers, 2021 to 2022). "The availability of characterized BRS3-Cre driver alleles facilitates investigation of BRS3 function in pancreatic islets, neuroendocrine tumors, and certain cancers." (PMID 34326065, 2021). "In addition, studies have shown that relative to normal tissue, primary neuroendocrine tumor expression of BRS3 was increased by 13-fold." (PMID 35422890, 2022).
type 2 diabetes (2 papers, 2015 to 2024). "ORI, as the found new ligand of BRS‐3, gives an important device compound to explore BRS‐3's capability, particularly for target approval in type 2 diabetes and corpulence." (PMID 38726411, 2024).
Anxiety (1 paper, 2017). Intense feelings of nervousness, tension, or panic often arise in response to interpersonal stresses. "Mild behavioral phenotypes have been reported in Brs3-/y mice, including a greater preference for saccharine and aversion to quinine, increased meal size, less anxiety in an elevated plus maze test and decreased response to social isolation." (PMID 29107299, 2017). "In anxiety assays (open field and elevated plus maze), no phenotype was detected in Brs3-/y mice." (PMID 29107299, 2017).
asthma (1 paper, 2021). "In contrast, another study in an animal model of asthma showed a beneficial effect of BRS-3 activation on asthma by promoting antigen uptake by HBECs and subsequently increasing T-cell proliferation and Th1 differentiation." (PMID 34948451, 2021). "Some of the studies described in the review based on animal models so far have shown beneficial effects in reducing asthma symptoms by activating nociception NOP1, bombesin BRS-3 and somatostatin SST4 receptors, or blocking the NPY-Y1 receptor." (PMID 34948451, 2021).
glioma (1 paper, 2021). A benign or malignant brain and spinal cord tumor that arises from glial cells (astrocytes, oligodendrocytes, ependymal cells). "One study investigated the mRNA expression levels of each of the human BnRs (GRPR, NMBR, BRS-3) in recurrent gliomas in nine patients." (PMID 34539578, 2021). "All gliomas had uptake and correlated with tumor density of GRPR, not NMBR/BRS-3." (PMID 34539578, 2021).
Insulin resistance (1 paper, 2017). Increased resistance towards insulin, that is, diminished effectiveness of insulin in reducing blood glucose levels. "Deletion of Brs3 in glutamatergic neurons expressing Vglut2 reproduced the global null phenotype for regulation of food intake, metabolic rate, body temperature, adiposity, and insulin resistance." (PMID 29107299, 2017). "Taken together, these data demonstrate that Brs3 expression in Vglut2, but not Vgat, neurons is necessary for proper regulation of food intake, metabolic rate, adiposity, adiposity sequelae (insulin resistance), and response to BRS-3 agonist." (PMID 29107299, 2017).
insulinoma (1 paper, 2015). "On the other hand, a Brs3 agonist promoted insulin secretion in both rodent insulinoma cell lines and in islets isolated from wild-type but not Brs3 mutants." (PMID 26020940, 2015).
small cell lung carcinoma (1 paper, 2022). Small cell lung cancer (SCLC) is a highly aggressive malignant neoplasm, accounting for 10-15% of lung cancer cases, characterized byrapid growth, and early metastasis. "It has been reported that BRS3 activation promotes metastasis formation and drug resistance in small cell lung cancer cells." (PMID 35422890, 2022).
cancer (5 papers, 2016 to 2022). A tumor composed of atypical neoplastic, often pleomorphic cells that invade other tissues. "This family of peptide receptors contains gastrin-releasing peptide receptor (GRPR), neuromedin B receptor (NMBR), and bombesin receptor subtype 3 (BRS3), which are overexpressed by a number of cancers, including PDAC." (PMID 29865257, 2018).
tumours (3 papers, 1999 to 2021). "RT-PCR analysis showed that OV-1063 tumours expressed mRNA for bombesin receptor subtypes BRS-1, BRS-2, and BRS-3." (PMID 10970693, 2000). "The mRNA levels for BRS-3, but not for BRS-2, were lower in the AN-215-treated tumours as compared with controls." (PMID 10576652, 1999).
BRS3 also shares sentences with these, for which no sentence is quoted: diabetes (2 papers); Hypertension (2); breast carcinoma (1); carcinoid (1); malignant glioma (1); Onset (1).